WWP1 (WW domain containing E3 ubiquitin protein ligase 1)
Diseases named in the same sentence as WWP1 in open-access papers (continued):
Sharing a sentence is not in itself a finding about the gene and the disease.
tumor (continued). "Taken together our study suggests tumor suppressor properties for CYYR1 through regulation of WWP1 autoubiquitination and lysosomal degradation." (PMID 39059493, 2024). "NDFIP1, an adaptor for NEDD4 family proteins, interacts with WWP1 and has potential anti-tumor effects." (PMID 39949609, 2024). "Genetic or pharmacological inhibition of WWP1 enhanced the effect of SHP2 inhibitor in suppressing tumor growth in vitro and in vivo." (PMID 39014007, 2024). "Functional studies indicated that miR-129-5p binds to the coding sequence of WWP1 mRNA, inhibiting GC cell proliferation and migration in vitro and slowing tumor growth in vivo." (PMID 39949609, 2024). "Collectively, these findings indicate that WWP1 overexpression inhibits the tumor-forming abilities of LN229 cells." (PMID 37568787, 2023). "Upregulated WWP1 has been reported in CRC and is associated with tumor size, T classification, distant metastasis, TNM stage, and adverse patient prognosis." (PMID 36831013, 2023). "There are direct pieces of evidence illuminating the oncogenic and tumor-suppressive roles of WWP1 and WWP2." (PMID 37568787, 2023). "DUBTACs (Deubiquitinase targeting chimeras), an extension of PROTACs technology, can recruit DUBs to counteract the degradation of tumor suppressors mediated by the WWP1 oncoprotein." (PMID 38129384, 2023). "On the one hand, the KLF5 locus at chromosome 13 is frequently deleted in human BC, and its protein is degraded by the WWP1 oncogenic ubiquitin E3 ligase, which suggests a tumour-suppressor function." (PMID 36765262, 2023). "In solid tumors, WWP1 plays a dual role as both an oncogene and a tumor suppressor, whereas in hematological malignancies such as AML, it is identified as a dedicated oncogene." (PMID 38129384, 2023). "In the xenograft models, the tumor volumes and weights were higher in the WWP1 overexpression group than in the control." (PMID 35264565, 2022). "Taken together, our findings suggest that WWP1 can serve as an oncogene or a tumor suppressor, depending on its interactions with different substrates." (PMID 36168627, 2022). "First, we explored the expression patterns of WWP1 in ICC between tumor tissues and paired adjacent normal liver tissues." (PMID 35264565, 2022). "Accumulating evidence demonstrates that WWP1 is aberrantly expressed in various types of malignancies, indicating that WWP1 serves as an oncoprotein or a tumor suppressor." (PMID 35264565, 2022). "Here, in this study we investigated the expression pattern, clinical prognosis, tumor biological functions, and molecular mechanisms of WWP1 in ICC." (PMID 35264565, 2022). "Double IF staining of CK19 and WWP1 showed that the expression of WWP1 was upregulated in CK19-positive tumor cells compared with that in CK19-positive epithelial cells of adjacent non-tumor tissues." (PMID 35264565, 2022). "The data revealed that silencing WWP1 greatly inhibited tumor growth, as shown by lower tumor volumes and lower weight in the WWP1 knockdown group compared to the control group." (PMID 35264565, 2022). "In these tumor tissues, WWP1 either promotes or inhibits tumorigenesis via modulating the protein levels or functions of its substrates." (PMID 34712671, 2021). "Though functioning as a tumor suppressor under some circumstances, WWP1 is generally accepted as an oncoprotein." (PMID 34712671, 2021). "Functionally, WWP1 has been demonstrated to play either an oncogenic role or tumor suppressive functions in various types of human tumors." (PMID 34226507, 2021). "Emerging evidence demonstrates that WW domain-containing E3 ubiquitin protein ligase 1 (WWP1) participates into carcinogenesis and tumor progression." (PMID 34226507, 2021). "Peptidyl-prolyl isomerase Pin1 interacted with p63α and impaired the binding between p63α and WWP1, resulting in inhibition of WWP1-mediated p63α degradation and promotion of cell proliferation and tumor formation." (PMID 34226507, 2021).
tumor (continued). "Taken together, these results suggest that downregulation of miR-584-5p contributes to tumor progression by downregulation of WWP1, thus, highlighting the potential of miR-584-5p as a therapeutic target for human GC." (PMID 28431583, 2017). "Quantitative RT-PCR showed that tissues from primary human HCC biopsies exhibited significantly higher expression rates of WWP1 mRNA compared to adjacent non-tumor tissues (30/42; 70.4%; P = 0.0003)." (PMID 26506518, 2015). "Expression of WWP1 protein was significantly elevated in 14/24 (58.3%) specimens of human primary HCC tissue compared to compared to adjacent non-tumor hepatic tissues (P = 0.004)." (PMID 26506518, 2015). "In conclusion, our study has identified WWP1 E3 ligase as a novel negative regulator of LATS1 tumor suppressor stability." (PMID 23573293, 2013). "It would be thus important to address the role of ezrin/WWP1 interaction in the regulation of Met activity in tumor cells and in metastasis as Met plays a central role in these processes." (PMID 22629406, 2012). "Our results link WWP1 and ezrin to the Met receptor activity, providing a molecular basis to the role of ezrin and WWP1 in tumor progression." (PMID 22629406, 2012). "Moreover, drug screening assays revealed that WWP1 depletion had an additive effect with the PI3K-AKT pathway inhibitors on hindering tumor growth." (PMID 39656237, 2025). "Identifying novel substrates is essential for elucidating WWP1's roles in tumor biology." (PMID 40280416, 2025). "Downregulation of WWP1 significantly inhibited tumor growth compared to the control group." (PMID 40280416, 2025). "In vivo xenograft studies confirmed that WWP1 depletion substantially inhibited tumor growth." (PMID 39656237, 2025). "WWP1’s critical role in tumor regulation lies in its interactions with ubiquitination substrates." (PMID 39949609, 2024). "Moreover, WWP1 overexpression increased MMP2 and MMP9 activity, proteins associated with tumor metastasis and angiogenesis." (PMID 39949609, 2024). "In in vivo experiments, tumor growth inhibition by MYCi361 administration was also observed, but the inhibitory effect of MYCi361 on the growth of tumor cells was significantly attenuated following WWP1 overexpression." (PMID 38997648, 2024). "These various studies indicate that WWP1 can act as a tumor suppressor depending on the context." (PMID 38129384, 2023). "Besides, downregulation of WWP1 leads to compromised tumor proliferation, as well as enhanced G0/G1-phase arrest and apoptosis by governing the PTEN/AKT signaling pathway." (PMID 36825281, 2023). "All of these studies indicate that WWP1 is an important tumor promoter and promising target in GC." (PMID 36825281, 2023). "Then, the expression of circWAC, miR-142 and WWP1 was evaluated in tumor tissues by qRT-PCR." (PMID 33648498, 2021). "High expression level or hyperactivation of WWP1 may abnormally enhance polyubiquitinations of some oncoproteins or tumor suppressors, such as ΔNp63α, PTEN and p27, and ultimately promote cell proliferation, survival, migration and invasion in tumorigenesis." (PMID 34712671, 2021). "Moreover, we will discuss the various functions of WWP1 as an oncoprotein or a tumor suppressor in a variety of malignancies." (PMID 34226507, 2021). "Thus, YAP and TAZ exert tumor promotion in part via blocking KLF5 from WWP1-involved degradation and stabilizing KLF5 activity." (PMID 34226507, 2021). "Considering that WWP1 overexpression accelerated tumor cell proliferation and survival and delayed cellular senescence, we evaluated the role of miR-584-5p in the regulation of GC cellular senescence by detection of SA-β-gal staining, which is considered a specific senescence marker." (PMID 28431583, 2017).
tumor (continued). "Colony formation and proliferation assays confirmed that silencing WWP1 inhibited cell growth; whereas migration and Matrigel invasion assays showed that it suppressed migration and invasion in vitro, indicating that WWP1 played a role in tumor metastasis." (PMID 26506518, 2015). "However, Ki67 expression was enhanced in tumor tissues stably overexpressing WWP1." (PMID 38997648, 2024). "However, we unexpectedly found that WWP1 had a tumor suppressor role." (PMID 36168627, 2022). "Notably, the tumor suppressor role of WWP1 in HCC was mediated by ARHGAP24 expression." (PMID 36168627, 2022). "Moreover, the expression of WWP1 was linked to tumor size, histological grade, TNM stage, vascular invasion, and tumor capsule of HCC patients, indicating that WWP1 might be an independent predicator of poor prognosis in HCC patients." (PMID 34226507, 2021). "Similarly, depletion of WWP1 reduced cell proliferation in vitro and blocked tumor growth in vivo." (PMID 34226507, 2021). "However, it should be cautious because WWP1 may as well have tumor-suppressive functions in some scenarios." (PMID 34712671, 2021). "Indeed, depletion of either PKCα or WWP1 abrogated TRIB3-enhanced tumor sphere formation; while TRIB3 depletion-impaired tumor sphere formation could be rescued by overexpressing the of EGFRT654D mutant but not the EGFRT654A or EGFRT654D/K689R mutants." (PMID 32694521, 2020). "Recently, it was demonstrated that WWP1-mediated K27 ubiquitination of PTEN suppresses dimerization, plasma membrane recruitment, and tumor suppressive function." (PMID 40991650, 2025). "Here, we demonstrate that TXNIP stability is negatively regulated by WWP1 in AML cells, a tumor in which additional therapeutic targets are needed." (PMID 39364720, 2025). "Recently, WWP1 was reported to ubiquitinate and inactivate PTEN, which in turn activates the PI3K-AKT pathway and contributes to tumor growth." (PMID 39656237, 2025). "The ubiquitination and degradation of PTEN by WWP1 reduces the PTEN protein levels, impairing its tumor suppressor function." (PMID 39144161, 2024). "Like WWP1, WWP2 is also involved in tumor progression through regulating the PTEN/AKT pathway in CRC." (PMID 36831013, 2023). "In CRC and PTC, WWP1 promotes invasion, metastasis, and TNM (Tumor; Node; Metastasis) stage by activating the PTEN/AKT signaling pathway (Fig. 5C2,)." (PMID 38129384, 2023). "Major histocompatibility complex (MHC) class I-mediated tumor antigen processing was the hub pathway that was significantly downregulated in lgCMN, and ITCH, FBXW7, HECW2, and WWP1 were identified as candidate hub genes." (PMID 34912899, 2021). "From our studies, WWP1 and Itch serve to balance LATS1 tumor suppressor activity through continuous ubiquitination and degradation of LATS1 under physiological (unstressed) condition." (PMID 23573293, 2013). "However, TAZ/YAP can protect KLF5 from WWP1-mediated degradation by binding to KLF5 through its WW domain, thereby promoting BC cell proliferation, survival, and tumor growth." (PMID 40535763, 2025). "Additionally, WWP1 modifies PTEN, another key tumor suppressor that also lacks a PY motif, inhibiting its localization on the plasma membrane and impairing its ability to resist PI3K activation." (PMID 39949609, 2024). "The IHC results revealed that the staining score of WWP1 in the ICC tumor tissues was higher than that in the paired adjacent non-tumor tissues." (PMID 35264565, 2022). "Consistently, WWP1 depletion in cutaneous SCCs and HNSCC cells decreases tumor cell proliferation." (PMID 32560247, 2020). "Indeed, depletion of either PKCα or WWP1 abrogated TRIB3-enhanced proliferation, invasion, and tumor growth." (PMID 32694521, 2020). "Immunohistochemical analysis confirmed that WWP1 expression was positive in primary HCC tissue samples but was negative in adjacent non-tumor tissues." (PMID 26506518, 2015).
tumor (continued). "It is therefore possible that WWP1, with four WW domains, may compete with YAP and TAZ for LATS1 binding to control the levels of tumor suppressor LATS1." (PMID 23573293, 2013). "Similarly, WWP1, SDC1 (syndecan 1), EZH2, CCND1, ADAM9 and MEMO1 have oncogenic activities and are targeted by the potentially tumor suppressor miRNA miR-195, miR-10b, let-7c, miR-17 and miR-125b." (PMID 21375733, 2011). "Western blotting showed that the levels of WWP1 were elevated in tumor tissues with low expression levels of NDFIP1, indicating a negative correlation between WWP1 expression and NDFIP1 in clinical cases." (PMID 35264565, 2022). "In addition, the negative correlation between WWP1 and miR-16 was found in CRC, and miR-16 could target WWP1 to suppress CRC tumor growth." (PMID 36831013, 2023).
infection (5 papers, 2013 to 2023). The state of being infected such as from the introduction of a foreign agent such as serum, vaccine, antigenic substance or organism. "We determined the functional relevance of ITCH and WWP1 to old-world arenavirus infection by investigating the effect of siRNA-mediated depletion of these proteins during infection by four old-world arenaviruses, including three that are pathogenic (LCMV, LASV, LUJV) and one that is not (MOPV)." (PMID 31906112, 2019). "At 48 hours post-infection, immunoblot analyses suggested that Lesh WWP1 could markedly inhibit the expression of endogenous WWP1." (PMID 23799152, 2013). "Notably, the role of WWP1 in inflammation and infection has also been unfolded." (PMID 35508474, 2022). "Here we demonstrated that WWP1, WWP2, and NEDD4 are overexpressed during SARS-CoV-2 infection and that their expression co-localizes with areas of infection in lung tissue both in mice and humans." (PMID 33762578, 2021). "As many RNA viruses are already known to recruit proteins from the Nedd4 family, including ITCH, to facilitate budding, we investigated the role of ITCH, WWP1 and its homolog WWP2 during infection by various old-world arenaviruses." (PMID 31906112, 2019). "Here, we also observed substantial increases in the mRNA expression of different HECT E3 ligases, specifically WWP1, WWP2, SMURF1 and NEDD4, in infected Vero E6 and Calu-3a cells, which could exacerbate infection." (PMID 36754974, 2023). "Although not statistically significant, the depletion of WWP1 and WWP2 moderately decreased infectious particles production for all assessed infections." (PMID 31906112, 2019).
neurological disorders (5 papers, 2023 to 2025). "Most importantly, small-molecule inhibitors, such as I3C, can inhibit the enzymatic activity of WW domain-containing E3 ubiquitin protein ligase 1 (WWP1), which is responsible for causing several neurological disorders." (PMID 39061415, 2024). "WWP1 can regulate neurological disorders by interacting with or ubiquitinating several key proteins." (PMID 38129384, 2023). "WW domain-containing E3 ubiquitin protein ligase 1 (WWP1, also known as AIP5 or TIUL1) is related to NEDD4 family members, contains four WW domains, and is primarily involved in inflammation, neurological disorders, cardiovascular diseases, and malignancies." (PMID 36825281, 2023).
cardiovascular diseases (2 papers, 2022 to 2023). "Although WWP1 is pivotal during the progression of cardiovascular diseases, its role in the heart is not fully understood." (PMID 36593958, 2023).
heart diseases (2 papers, 2020 to 2023). "This seminal study has verified that WWP1 is highly expressed in cardiomyocytes, and reported its role in regulating cardiomyocyte phenotypes may help identify novel targets for therapeutic intervention during the progression of heart diseases." (PMID 36593958, 2023). "Among the nine members of the NEDD4 family, NEDD4-1, NEDD4L, ITCH, WWP1, WWP2, SMURF1 and SMURF2 are involved in heart diseases." (PMID 33110392, 2020).
adenocarcinoma (1 paper, 2019). A common cancer characterized by the presence of malignant glandular cells. "A total of 72 h after transfection of the siRNA, human adenocarcinoma alveolar basal epithelial (A549) cells were efficiently depleted for ITCH, WWP1 or WWP2, as compared to cells transfected with a non-targeting (NT) control siRNA." (PMID 31906112, 2019).
hematological malignancies (1 paper, 2023). "WWP1 is also implicated in the dysregulation of solid tumors and hematological malignancies, impacting patient survival." (PMID 38129384, 2023).
neurodevelopmental disorder (1 paper, 2026). A behavioral and cognitive disorder with onset during the developmental period that involves impaired or aberrant development of intellectual, motor, or social functions. "Biochemical and in vivo functional analyses characterize the variant as GOF, supporting the clinical relevance of WWP1 dysregulation in neurodevelopmental disorders." (PMID 41786693, 2026).
WWP1 also shares sentences with these, for which no sentence is quoted: infectious disease (3 papers); autism spectrum disorder (2); lung adenocarcinoma (2); papillary thyroid cancer (2); breast (1); breast invasive carcinoma (1); chordoma (1); Cirrhosis (1); colon adenocarcinoma (1); cutaneous squamous cell carcinoma (1); dwarfism (1); dystroglycanopathy (1); head and neck squamous cell carcinoma (1); hereditary spastic paraplegia (1); Hypertension (1); IgA nephropathy (1); inflammatory bowel disease (1); Insulin resistance (1); LIG4 syndrome (1); metabolic disorders (1); neurodegenerative disease (1); non-ischemic cardiomyopathy (1); non-small cell lung carcinoma (1); ovarian carcinoma (1); pancreatic adenocarcinoma (1); prostate adenocarcinoma (1); prostate hyperplasia (1); pulmonary fibrosis (1); renal fibrosis (1); sarcopenia (1).
A further 6 diseases each share a sentence with WWP1 in 1 paper.